VIM (vimentin)
Diseases named in the same sentence as VIM in open-access papers (continued):
Sharing a sentence is not in itself a finding about the gene and the disease.
tumor (continued). "As anticipated, loss of E-cadherin and gain of twist, snail, and vimentin were detected in subcutaneous tissues from CCL7 overexpressing HCT116 tumor." (PMID 27167205, 2016). "This tumor is frequently associated with more frequent lymphatic metastasis, higher Ki67 labeling index, more advanced stage disease as well as simultaneous vimentin upregulation and E-cadherin downregulation." (PMID 27583684, 2016). "EMT, which is characterized by epithelial marker (E-cadherin) down-regulation or loss and mesenchymal marker (vimentin) up-regulation, is a crucial step in tumour invasion and metastasis." (PMID 27759077, 2016). "Overexpression of Slug causes EMT, which leads to tumor aggressiveness by upregulation of the mesenchymal markers vimentin and fascin and down-regulation of epithelial markers E-cadherin, occludins, and claudins." (PMID 26918943, 2016). "The expression of α-SMA, the most reliable marker of tumour associated fibroblasts (TAFs) and vimentin, showed a clear and gradual increase in WJ-MSCs up to a maximum at day 16 when WJ-MSCs were cocultured with WHCO1 cells (data not shown)." (PMID 26880967, 2016). "Vimentin is a filament that is highly expressed in mesenchymal cells and is generally used to determine those tumor cells that are undergoing EMT based on the positive association of Vimentin expression with the invasion and metastasis in multiple cancers." (PMID 27188458, 2016). "Abnormal vimentin expression is associated with a high tumour grade such as cancer of the lung and bladder and other studies revealed a positive correlation between extensive vimentin expression and the occurrence of metastasis." (PMID 27190522, 2016). "Expression of periostin is associated with vimentin expression in the stroma or tumor epithelia and correlates with higher stage." (PMID 27018053, 2016). "The levels of CD163 expression in tumor cells were positively associated with the expression of E-cadherin (P = 0.04 and P = 0.038, respectively) and vimentin (P < 0.001 and P < 0.001, respectively) in tumors and at the tumor invasion front." (PMID 26769084, 2016). "The epithelial–mesenchymal transition (EMT) associated markers vimentin, N-cadherin, and E-cadherin have essential roles in the invasion of tumor cells." (PMID 27344168, 2016). "Mesenchymal or EMT CTC, as represented by vimentin expression in this study, have previously been associated with tumour invasiveness, chemoresistance, CTC clustering, stem cell characteristics, and poorer clinical outcomes." (PMID 26923772, 2016). "The present study results confirmed that vimentin expression is associated with the grade of the tumour." (PMID 26640315, 2015). "Most importantly, we found that the expression of Sufu inversely correlated with the expression of vimentin and positively associated with the expression of E-cadherin in the tumor cells from human LAD patients." (PMID 26462018, 2015). "EMT is characterized by up-regulation of mesenchymal markers (such as Vimentin) down-regulation of epithelial markers (such as E-cadherin), and loss of cell–cell adhesion, which enables tumor cells to dissociate and migrate from the primary tumor." (PMID 26692820, 2015). "Similar changes in cell cycle regulators cyclin D1 and p21 as well as EMT-associated genes including E-cadherin, N-cadherin, and vimentin were observed in tumor tissues by IHC." (PMID 25887760, 2015). "It was associated with concomitant presence of HLA-DR(+) stromal cells and RA in tumor cells (both p < 0.001), and inversely associated with vimentin expression in tumor cells (p = 0.036)." (PMID 26305673, 2015). "Stromal periostin protein is associated with versican collagen, and tumor cell epithelial periostin is associated with both versican and vimentin." (PMID 25852822, 2015). "Vimentin is often considered a marker for tumors of mesenchymal origin, and vimentin expression is increased in numerous epithelial tumors and is closely associated with tumor invasion." (PMID 25120657, 2014).
tumor (continued). "The high expression of Vimentin in cancer is associated with accelerated tumor growth invasion and poor prognosis." (PMID 25244643, 2014). "The rise in Vimentin expression has been reported to be associated with tumor migration, invasion and metastasis." (PMID 24959847, 2014). "The downregulation of E-cadherin and overexpression of vimentin were associated with tumor invasive pattern, lymphatic metastasis, and poor prognosis (P < 0.01)." (PMID 24758906, 2014). "A similar condition was observed also in PC3 and LNCaP xenografts where tumor masses contain a complex net of associated fibroblasts as evidenced by staining for vimentin and αSMA." (PMID 24597899, 2014). "Induction of EMT by incomplete RFA were demonstrated in xenograft tumors of both cell lines by western blot, and were characterized by the loss of E-cadherin and up-regulation of N-cadherin and vimentin in the tumor tissues of incomplete RFA group." (PMID 25542041, 2014). "We also observed E-cadherin loss and the upregulation of vimentin expression in the transformed tumor cells, which suggested that the increase in metastasis was induced by epithelial-to-mesenchymal transition." (PMID 24845259, 2014). "Vimentin expression was significantly associated with Lauren classification, depth of tumor invasion, and lymphovascular invasion (P < 0.05)." (PMID 24887009, 2014). "Paradoxically, inhibition of HDAC also induced epithelial-mesenchymal transition (EMT) in HNSCC cells, accumulation of BMI-1, an oncogene associated with tumor aggressiveness, and expression of the vimentin mesenchymal marker." (PMID 23527004, 2013). "The expression of vimentin is associated with enhanced motility of tumor cells and hence overexpression of vimentin by enhanced expression of SMC1 shows its role in maintenance of cell adhesion and metastasis." (PMID 23717600, 2013). "3P scaffolds induced tumor cells to undergo the epithelial-to-mesenchymal transition (EMT) as demonstrated by up-regulation of vimentin and loss of E-cadherin expression." (PMID 24146752, 2013). "In particular, changes were observed in the expression levels of stathmin and vimentin, which are proteins associated with tumor growth, while the tumor cell invasion and tumorigenesis dramatically decreased." (PMID 23946791, 2013). "An immunohistochemical study using the EMT-associated markers E-cadherin and vimentin, showed a variety of expression patterns in the 20 pairs of primary tumor tissue samples and MPE cell blocks." (PMID 23658677, 2013). "Most recently a study suggested that epithelial-mesenchymal transition (EMT) led to loss of E-cadherin and gain of vimentin that induces tumor cell dissemination from the primary tumor site." (PMID 23110497, 2012). "In particular, 12 genes, including AXL, CDH1, CFLAR, FKBP1A, NT5E, and VIM, were reported to be significantly associated with tumor metastasis (P<8E-04)." (PMID 23185353, 2012). "Most recently, a report demonstrated that EMT with loss of E-cadherin and gain of vimentin induces ACC cells to break away from the primary tumor site, suggesting ACC uses unique mechanisms of invasion from those of other malignant tumors of the oral cavity." (PMID 23110497, 2012). "Previous studies have found associations between vimentin expression and cancer cell morphology in tumour xenografts." (PMID 21448168, 2011). "The tumour microenvironment-associated stromal fibroblasts exhibited a homogeneous expression of vimentin at both the primary and metastatic sites in 38 of 39 (97%) paired cases." (PMID 21897388, 2011). "Multiple reports confirm the presence of typical EMT markers such as expression of vimentin, loss of E-cadherin, and nuclear beta-catenin accumulation at the invasive edge of a tumor." (PMID 24281215, 2010). "Vimentin expression is associated with high tumor invasiveness; in our cohort, vimentin expression was found only in basal-like and in HER2+/ER- tumors." (PMID 20209131, 2010).
tumor (continued). "Additional PEA3 family target genes implicated in neoplasia include; urokinase plasminogen activator (uPA), vimentin, cyclooxygenase-2 (COX-2), Twist, MUC4, WT1, osteopontin, mammaglobin, cyclin D3 and HER2." (PMID 20107508, 2010). "Tumor progression is frequently associated with the downregulation of E-cadherin, and upregulation of vimentin and several transcription factors including Snail, Twist and Slug." (PMID 20718984, 2010). "Vimentin expression, a rather rare occurrence in invasive breast cancer, is associated with high tumor invasiveness and with in vitro chemosensitivity." (PMID 20209131, 2010). "The expression of the mesenchymal markers vimentin and N-cadherin and loss of the epithelial marker E-cadherin suggests these once epithelial tumor cells have undergone an EMT; characteristic of aggressive, invasive cells such as CSCs." (PMID 24281215, 2010). "Immunohistochemistry is of diagnostic value and the tumour is stained positive to S-100, vimentin, epithelial membrane antigen and cytokeratin antibodies." (PMID 18279530, 2008). "Recent studies have identified vimentin, a type III intermediate filament, among genes differentially expressed in tumours with more invasive features, suggesting an association between vimentin and tumour progression." (PMID 17325702, 2007). "Recently, an association between vimentin and tumour development, progression, and chemosensitivity was suggested by various gene profiling studies." (PMID 17325702, 2007). "A multitude of studies gave evidence that the expression of vimentin in carcinomas has to be interpreted as a sign of an epithelial-mesenchymal transition, associated with high tumour aggressiveness." (PMID 16412231, 2006). "Vimentin expression was strongly associated with markers of tumor invasiveness and may serve as a practical prognostic biomarker in ccRCC." (PMID 40831933, 2025). "Our findings that vimentin expression in tumor tissues is significantly associated with Ki67 expression in TNBC patient tissues, is consistent with the previously reported association of vimentin expression with high Ki67 expression and poor prognosis for TNBC patients." (PMID 41279138, 2025). "From a clinical perspective, the consistent associations observed for Vimentin suggest that its expression may serve as a practical surrogate for tumor aggressiveness." (PMID 40831933, 2025). "The mesenchymal marker vimentin is strongly linked with tumor migration and invasion." (PMID 40657397, 2025). "Our data indicate that vimentin might play a role in tumor cell dissemination, which in turn is associated with recurrence and metastasis." (PMID 40558484, 2025). "Moreover, VIM expression is associated with larger tumor size, lymph node metastasis, and distant metastasis in ESCC, highlighting the significance of VIM expression in the progression of ESCA." (PMID 40529228, 2025). "Considering that MMP9, E-cadherin, and Vimentin are linked to tumour invasion and metastasis — with Ki-67 serving as an indicator of cell proliferation — we verified their expressions in the pL-NC-LM3 and pL-sh-AC026412.33-LM3 groups via IHC and qRT-PCR analyses." (PMID 40790550, 2025). "Collectively, these multimodal data demonstrate that hypoxia‐induced tumor cell migration is mechanistically linked to vimentin filament reorganization, with cytoskeletal dynamics potentially serving as a hypoxia‐responsive regulator of experimental metastatic competence." (PMID 40884268, 2025). "Understanding the implications of vimentin expression could provide insights into the mechanisms underlying tumor progression and metastasis." (PMID 41155869, 2025). "Furthermore, loss of PBRM1 in preexisting PDAC caused a shift in the tumor grade from a well- to a poorly differentiated state, concomitant with increased vimentin expression." (PMID 40454484, 2025).
tumor (continued). "Additionally, there was increased expression of E-cadherin and decreased expression of vimentin, which are associated with tumor suppression and progression, respectively." (PMID 39868366, 2024). "Tumor cell morphology was altered from flattened to spindle-shaped and produced more pseudopods, causing elevated cell proliferation, DNA synthesis, migration ability, and protein levels of migration-related markers vimentin and twist." (PMID 38711855, 2024). "In addition, loss of cytokeratin and gain of vimentin expression indicate aggressive tumor behavior." (PMID 38360653, 2024). "Among these processes, epithelial‐mesenchymal plasticity (EMP), particularly epithelial‐mesenchymal transition (EMT), plays a pivotal role in driving tumor malignancy and invasiveness, characterized by the loss of epithelial markers and the gain of mesenchymal markers such as vimentin." (PMID 38864546, 2024). "Notably, loss of vimentin has been demonstrated to significantly induce proliferation in several cancer cell lines and promote tumor growth in xenograft in vivo models through increased phosphorylation of AKT and upregulation of β-catenin signaling." (PMID 39516342, 2024). "Additionally, cancer cells produce exosomes that contain VIM, and these exosomes are taken up by tumor-associated macrophages (TAMs), inducing cytoskeletal rearrangement and polarization of the TAMs, making them tumor-supporting." (PMID 39766058, 2024). "Additionally, this work gives causal context to clinical data associating vimentin expression with tumor progression in patients." (PMID 37161053, 2023). "Finally, further investigation is warranted to elucidate the mechanism underlying the relationship between vimentin expression and unclear tumor borders." (PMID 37717112, 2023). "Extensive study has proven an association between vimentin and tumor invasion and metastasis." (PMID 37718450, 2023). "Several investigations have linked vimentin to tumor invasion and metastasis." (PMID 37718450, 2023). "However, a ten-day co-culture of tumor cells in contact with NFs induces EMT in the tumor, with loss of E-cadherin and the characteristic tumor growth phenotypes and induction of vimentin, and acquisition of metastatic potential in vivo." (PMID 37046676, 2023). "In addition, GO analysis implicated vimentin in cell migration, and KEGG pathway enrichment analysis implicated vimentin in tumor-invasive metastasis." (PMID 37833712, 2023). "It is characterized by decreased of epithelial markers such as E-cadherin and increased of mesenchymal markers such as N-cadherin and Vimentin; This leads to the weakening of intercellular adhesion and the loss of cell polarity, and finally enhances the ability of tumor invasion and migration." (PMID 37863960, 2023). "Additionally, it was observed that the presence of more circulating tumor cells with positive qualitative markers (vimentin, N-cadherin) was associated with a poorer prognosis for patients." (PMID 37841010, 2023). "We hypothesize that the lower expression of Cx37, Cx40, and Panx-1 and the higher expression of vimentin may be associated with a more aggressive tumor phenotype, possibly by regulating growth and tumorigenic properties." (PMID 36833374, 2023). "On the flip side, vimentin may also regulates other microRNAs with tumor suppressing function, thus promoting increased invasiveness and other tumor-associated properties pro when it is present in mesenchymal cells." (PMID 36230521, 2022). "Vimentin expression is linked to migration and tumour cells metastasis." (PMID 36362433, 2022). "A motility gene expression study indicated that SMAD3 selectively increased the expression of ITGB2 and VIM, two genes that were found to be implicated in hypoxia-induced cell invasion and associated with tumor progression and metastasis in cohorts of cancer patients." (PMID 35681731, 2022).
tumor (continued). "Tumor invasion and metastasis are generally associated with epithelial-mesenchymal transition, which is a cellular process accompanied with the loss of epithelial marker (E-cadherin, etc.)and increase in mesenchymal markers (N-cadherin, vimentin, etc.)." (PMID 36147842, 2022). "Furthermore, cellular stress and autophagy, e.g., during chronic inflammation and tumor progression, can cause citrullination of vimentin." (PMID 35606362, 2022). "While studies have documented statistical associations between higher vimentin expression and cancer progression through tumor stages and increased metastasis, its expression was not limited to the invasive front of tumor cells or other histological measures of invasiveness." (PMID 35207438, 2022). "Once initiated cells appear, the depletion of vimentin may break the balance of inflammation-associated protumorigenic and antitumorigenic effects, thus promoting the tumor growth." (PMID 35399505, 2022). "The involvement of S100A4 in EMT and MM has been previously documented in a large collection of 109 tumor specimens from patients, showing its specific high expression in the sarcomatoid histological subtype, together with vimentin and ZEB1, linked to aggressive features." (PMID 35873564, 2022). "Snail and vimentin are also thought to be associated with increased tumor aggressiveness." (PMID 35645793, 2022). "Neoplasia-associated EMRCs showed a mean Ki67 labeling index of 12.6% (range 0–30%); with nuclear atypia in 16/20 (80%) cases; diffuse p16 expression in 15/20 (75%) cases; and heterogeneous ER, PR, and vimentin expression." (PMID 35054228, 2021). "While the upregulation of Vimentin is strongly associated with tumor cell invasion and metastasis." (PMID 34630125, 2021). "The dual expression of Vimentin and αSMA observed within tumour‐associated stromal cultures, indicative of a myofibroblast‐like phenotype, is consistent with the stromal alterations seen in vivo and the accumulation of myofibroblasts (vimentin+ αSMA+) within the prostate interstitium." (PMID 34596356, 2021). "Yet, it is unclear, whether histogram parameters derived from DCE-MRI are associated with the amount of TIL, tumor-stroma ratio and vimentin expression in HNSCC." (PMID 34801089, 2021). "The EMT-like process of tumor cells includes the reduction of cell adhesion proteins such as E-cadherin, and the rise in mesenchymal markers such as N-cadherin and vimentin, leading to reduced intercellular adhesion and loss of cell polarity and ultimately enhancing tumor invasion and migration." (PMID 34868922, 2021). "Moreover, we found that the expression of vimentin protein was associated with HBX in HBV-related tumor tissues." (PMID 33722250, 2021). "In addition, undergoing EMT usually leads to the loss of E-cadherin expression and increase in vimentin expression in metastatic tumor tissues." (PMID 34912458, 2021). "Additionally, there was a positive correlation between CD44 and vimentin (a marker of EMT) expression level, and the levels of both CD44 and vimentin are associated with MEC tumor grade." (PMID 35048028, 2021). "Furthermore, secreted extracellular Vimentin is associated with the spheroid formation of glioblastoma cancer stem cells, which is consistent with the acquisition of stemness in tumor cells undergoing EMT." (PMID 33530981, 2021). "Similarly, when Sutent was tested, although Sutent causes inhibition of tumor growth and mesenchymal markers (e.g., vimentin), the expression of EMT-regulating transcription factor slug was induced." (PMID 34064322, 2021). "Vimentin’s high expression was associated with tumor progression and metastasis." (PMID 33673439, 2021). "More studies are clearly needed to better understand the underlying mechanisms and to evaluate whether vimentin high sub-population can be manipulated to unveil the ever-elusive status of tumour drug resistance and recurrence." (PMID 34203746, 2021).